EIF1AX (eukaryotic translation initiation factor 1A X-linked)
Diseases named in the same sentence as EIF1AX in open-access papers (continued):
Sharing a sentence is not in itself a finding about the gene and the disease.
metastatic disease (4 papers, 2017 to 2024). "BAP1 and SF3B1 mutations are found most frequently in metastatic disease, whereas EIF1AX gene mutation is related to a favorable prognosis." (PMID 38175637, 2024). "Although BAP1–located on chromosome 3–correlates well with the chromosome 3 status and a BAP1 mutation is associated with a high likelihood for metastatic disease, EIF1AX and SF3B1 occur typically in disomy 3 tumors." (PMID 34439147, 2021). "As EIF1AX mutations are associated with a low risk of developing metastatic disease, additional functional studies are required to determine the specific mechanisms by which EIF1AX mutations provide a selective advantage to UM cells in which they are present." (PMID 28594900, 2017).
papillary thyroid carcinoma (4 papers, 2017 to 2022). "The Cancer Genome Atlas (TCGA) study was the first landmark study to describe the mutation of EIF1AX in thyroid tumors, more specifically in papillary thyroid carcinoma (PTC)." (PMID 36551583, 2022). "EIF1AX is the first translation initiation factor reported as recurrently mutated in cancer, and is significantly mutated in both UM and papillary thyroid carcinoma." (PMID 28594900, 2017). "Since The Cancer Genome Atlas (TCGA) study, EIF1AX mutations have been primarily reported in poorly differentiated thyroid carcinoma (PDTC) and anaplastic thyroid carcinoma (ATC), but also in well-differentiated thyroid carcinoma (WDTC) and benign thyroid nodules, although less frequently." (PMID 36551583, 2022).
breast carcinoma (3 papers, 2020 to 2025). "In this study, we found that EIF1AX promoted the occurrence of breast cancer through transcriptional regulation of cell cycle elements." (PMID 32926483, 2020). "These analyses indicate that elevated EIF1AX expression positively correlated with poor survival in patients with breast carcinoma." (PMID 32926483, 2020). "We demonstrate that EIF1AX facilitates cell proliferation of breast cancer and tumorigenesis, possibly by promoting the G1/S transition." (PMID 32926483, 2020). "In this study, we show that levels of EIF1AX are significantly upregulated in breast cancer samples and that there is a positive correlation between EIF1AX expression levels and worse survival rates for patients with breast cancer." (PMID 32926483, 2020). "Flow cytometry, ChIP and luciferase assays were used to investigate the molecular mechanisms by which EIF1AX regulates p21 in breast cancer cells." (PMID 32926483, 2020). "In summary, we show that EIF1AX expression is elevated in breast carcinomas and there is positive correlation between EIF1AX expression level and poor survival rates of breast cancer patients." (PMID 32926483, 2020). "Using immunohistochemistry, we detected the expression of EIF1AX in paired adjacent normal mammary tissues and mammary carcinoma tissues." (PMID 32926483, 2020). "EIF1AX was higher in breast cancer cells than that in normal breast epithelial cells at both mRNA and protein levels." (PMID 32926483, 2020). "Compared with adjacent normal tissues, EIF1AX mRNA had increased in the majority of breast carcinoma tissues." (PMID 32926483, 2020). "In brief, these results indicate that EIF1AX facilitates the G1/S transition, resulting in the promotion of breast cancer cell proliferation." (PMID 32926483, 2020). "The expression of EIF1AX in breast cancer tissues was detected by qRT‐PCR and immunohistochemistry staining." (PMID 32926483, 2020). "First, we detected the regulation of the cell cycle in breast cancer cells with EIF1AX overexpression or knock‐down." (PMID 32926483, 2020). "In breast cancer, about 2.4% and 0.9% of cases were reported to have genomic alterations for eif1 or eif1ax, respectively." (PMID 32708122, 2020). "To illustrate the role of EIF1AX in breast cancer tumorigenesis in vitro, we performed colony formation assays and found that the number of colonies formed increased following EIF1AX overexpression, whereas EIF1AX knock‐down reduced the number of colonies formed." (PMID 32926483, 2020). "We identified p21 as a downstream target of EIF1AX in breast cancer cells." (PMID 32926483, 2020). "We hypothesized that the abnormal expression of EIF1AX in breast cancer cell lines and mammary tumours may have pathological relevance." (PMID 32926483, 2020). "Furthermore, we found that p21 mRNA levels in tumour tissues were negatively related to EIF1AX levels (P < .01), which demonstrates that EIF1AX was negatively correlated with p21 expression levels in breast cancer." (PMID 32926483, 2020). "However, as a translation initiation factor, EIF1AX may also promote the occurrence of breast cancer by influencing the translation of other key factors, which can be further explored in future studies." (PMID 32926483, 2020). "We further determined the role of p21 downregulation in promoting EIF1AX‐dependent breast cancer cell proliferation by knocking down both p21 and EIF1AX to determine whether p21 knock‐down could rescue the EIF1AX knock‐down‐induced accumulation of cells in the G0/G1 phase." (PMID 32926483, 2020). "Firstly, the mRNA expression and protein expression of EIF1AX were examined in normal human breast epithelial cells (MCF‐10A) and several breast cancer cell lines." (PMID 32926483, 2020). "However, the expression and function of EIF1AX in breast cancer have not yet been investigated." (PMID 32926483, 2020).
carcinoids (3 papers, 2019 to 2025). "Interestingly, mutations in genes implicated in chromatin remodeling and histone modification are exclusive (such as EIF1AX) or generally more frequent in carcinoids as compared with large-cell and small-cell neuroendocrine carcinomas." (PMID 33641055, 2021). "In fact, although mutation rates of EIF1AX and ARID1A are in line with those of typical carcinoids, a higher prevalence of MEN1 mutations is observed in atypical carcinoids as compared with typical carcinoids, reaching 25%." (PMID 33641055, 2021). "Overall, based on histopathology, OTP expression, and/or presence of genomic alterations that, although not entirely specific, are highly characteristic of carcinoid tumors (MEN1 and EIF1AX), 55% of aSCLC exhibited features of a histogenetic relationship with pulmonary carcinoids." (PMID 39185963, 2025).
thyroid (3 papers, 2016 to 2021). "The important role of the EIF1AX gene in thyroid tumorigenesis came up also by the NGS studies on PDTC, ATC and FTC in which an EIF1AX gene mutation was found in 11%, 9%–13% and 5.1% of cases, respectively." (PMID 33572167, 2021).
endometrial carcinoma (2 papers, 2015 to 2025). A malignant tumor arising from the epithelium that lines the cavity of the uterine body. "The preliminary findings indicated that the aberrant subcellular localization of EIF1AX in endometrial cancer is significantly correlated with a poor prognosis." (PMID 41405406, 2025).
iris melanoma (2 papers, 2019 to 2025). A uveal melanoma that arises from the iris. "GNAQ, Guanine nucleotide-binding protein subunit alpha-11 (GNA11), EIF1AX, and BAP1 are commonly identified mutations in iris melanoma." (PMID 40491523, 2025).
meningeal melanoma (2 papers, 2022 to 2024). "The presence of SF3B1–, EIF1AX–, or BAP1–mutation or complex copy number variations indicate aggressive behavior consistent with meningeal melanoma." (PMID 36497333, 2022). "Furthermore, some additional molecular alterations, such as SF3B1, EIF1AX, and BAP1 mutations, confer a significant aggressive course in meningeal melanoma, while both primary diffuse leptomeningeal melanocytosis or melanomatosis are often NRAS mutated and rarely BRAF mutated." (PMID 39061148, 2024).
serous ovarian carcinomas (2 papers, 2022 to 2023). "Significant co-occurrence of mutations in NRAS and EIF1AX was also found in low-grade serous ovarian carcinomas." (PMID 36589683, 2022). "Dariush and colleagues demonstrated that NRAS, an oncogenic driver in serous ovarian carcinomas, could co-expressed with EIF1AX, which promoted clonogenicity and proliferation in OV." (PMID 37730669, 2023).
adenoma (1 paper, 2024). A neoplasm arising from the epithelium. "Most over-represented proteins in the adenoma cell line ZMTH3 were associated with RNA-binding and protein expression (EIF1AX, CSRP1, PPIC), suggesting enhanced protein biosynthesis activity." (PMID 39462388, 2024).
follicular thyroid cancer (1 paper, 2025). "Mutations in the EIF1AX gene (eukaryotic translation initiation factor 1A, X-linked) are an important genetic biomarker in follicular thyroid cancer." (PMID 39744583, 2025). "Mutations in the EIF1AX gene can alter the function of this factor and contribute to the development and progression of follicular thyroid cancer." (PMID 39744583, 2025).
Intellectual disability (1 paper, 2023). "Loss of function variants in SH3KBP1 are most commonly detected in patients with IMD61, but findings on two families with intellectual disability and large duplications encompassing SH3KBP1, EIF1AX, and RPS6KA3 genes indicate a possible role for SH3KBP1 in addition to that of RPS6KA3." (PMID 37510394, 2023).
iris tumours (1 paper, 2020). "As EIF1AX mutations are correlated with a good prognosis in UM, this could be one of the explanations for the relatively good survival of patients with an iris tumour in comparison to more posteriorly located UM." (PMID 32998469, 2020). "As in UM, mutations in BAP1, EIF1AX and SF3B1 are frequently seen in iris tumours." (PMID 32998469, 2020).
ovarian tumours (1 paper, 2015). "Exome sequencing identified two novel candidate genes, EIF1AX and USP9X, which are enriched in LGSC compared to SBT, suggesting they may be key contributors to carcinogenesis, although the biological impacts of mutant EIF1AX and USP9X in ovarian tumours remains to be determined." (PMID 26506417, 2015).
tumor (40 papers, 2015 to 2025). "Previous studies have found a close association between SF3B1 and EIF1AX gene mutations and tumor metastasis, with most UVM patients with SF3B1 mutations eventually developing metastasis." (PMID 40703526, 2025). "Based on the known mutational status of the respective primary tumours, EIF1AX mutations were successfully identified in 6/6 vitreous fluid samples, SF3B1 mutations in 6/8 samples and BAP1 mutations in 5/5 samples." (PMID 40240901, 2025). "Still, additional mutations in BAP1, SF3B1 and EIF1AX were detected in 15/17 samples and chromosome 3p and 8q copy numbers matched the primary tumour in 19/21 and 18/20 samples, respectively." (PMID 40240901, 2025). "EIF1AX mutations are commonly found in tumor cells in heterozygosis, indicating that EIF1AX functions as a dominant-acting oncogene." (PMID 36765733, 2023). "In the positive ion mode, F1-scores were 0.65, 0.35, and 0.64 for patients harboring a BAP1, SF3B1, and EIF1AX-mutated tumor, respectively." (PMID 36982149, 2023). "e.g., if cytogenetic, genetic or epigenetic changes associated with a more favorable prognosis such as disomy 3, or mutations in EIF1AX or SF3B1 are relatively more common in the north -even though tumor dimensions are similar." (PMID 36310339, 2022). "UM tumors often harbor a tumor-initiating mutation in GNAQ or GNA11 with secondary mutation in EIF1AX, SF3B1, SRSF2, or BAP1 that determines metastatic potential." (PMID 34771666, 2021). "It should be noted that the risk of metastasis highly depends on genetic mutations (BAP1, SF3B1, and EIF1AX) in the tumor." (PMID 34830810, 2021). "Mutations in eukaryotic initiation factor 1A (EIF1AX) are thought to occur in cases of disomy 3, rarely presenting in monosomy 3 tumours, consolidating its relatively low metastatic risk 24-26." (PMID 34149931, 2021). "In examining five key mutations in UM (GNAQ, GNA11, BAP1, SF3B1 and EIF1AX), the xenograft tumours matched the genomic signature of the original patient tumours in 83% of cases." (PMID 34149931, 2021). "EIF1AX mutations are associated with a good prognostic outcome; tumours with an SF3B1 mutation lead to an intermediate prognosis, in contrast to UMs with a BAP1 mutation." (PMID 32998469, 2020). "Co-occurrence of EIF1AX and H/N/K-RAS mutations is correlated with tumor aggressiveness, especially when it is the A113_splice mutations for EIF1AX gene." (PMID 31077238, 2019). "Most UMs harbor one Gq pathway mutation (GNAQ, GNA11, CYSLTR2, or PLCB4), one BSE mutation (BAP1, SF3B1, or EIF1AX), and a few recurrent CNAs, in 100% of tumor cells." (PMID 29317634, 2018). "Mutations in the EIF1AX gene have been detected in tumours that typically be deficient in other common drivers and identified in 1.5% of The Cancer Genome Atlas (TCGA) cohort, which are indicating that EIF1AX gene may play a role a novel PTC oncogene." (PMID 39558949, 2024). "Prognostically-relevant molecular tumour subtypes can be distinguished based on the presence of additional drivers: a so-called ‘BSE mutation’ in BAP1, SF3B1 or EIF1AX and copy number alterations (CNAs) affecting chromosome 3p or 8q." (PMID 40240901, 2025). "Using paired normal and tumor DNA from the same patients, we identified and validated a few novel recurrent somatic mutations in LGSOC, in addition to KRAS, BRAF, USP9X, and EIF1AX mutations that have been identified in previous studies." (PMID 36528667, 2022). "These primary mutation events contribute to tumor initiation while subsequence mutations in other genes, such as BAP1, SF3B1, and EIF1AX, contribute to tumor progression and metastasis." (PMID 34706158, 2022). "EIF1AX and SF3B1 mutations occur especially in low-risk D3 tumours, while BAP1 mutations are observed in most high-risk M3 UM." (PMID 34439175, 2021). "All but one tumour have a known UM driver gene mutation (GNAQ, GNA11, BAP1, PLCB4, CYSLTR2, SF3B1, EIF1AX)." (PMID 32415113, 2020).
tumor (continued). "In the replication cohort, metabolite abundancies are slightly different in the BAP1 group, with F1-scores of 0.82, 0.59, and 0.59 for patients harboring a BAP1, SF3B1, and EIF1AX-mutated tumor in the negative ion mode, respectively." (PMID 36982149, 2023). "It must be considered whether the changes seen in SF3B1 and EIF1AX are the driver mutation of POM, or a secondary change in the tumour." (PMID 30558566, 2018). "Tumor size-related proteins were involved in angiogenesis (VCAN, VTN, NRP1), EMT (FN1, CD44, THBS2), and translation (EIF1AX, EIF5), further indicating the biological basis of ccRCC growth." (PMID 37460463, 2023). "EIF1AX mutations were associated with Class 1 tumors (p < 0.0001), PRAME(-) status (p < 0.0001), decreased tumor diameter (p < 0.0001), lack of ciliary body involvement (p < 0.0001), and male sex (p < 0.0001)." (PMID 41387680, 2025). "For example, gene expression class, BAP1, SF3B1, EIF1AX, and chromosome 3 status, presence or absence of vasculogenic mimicry, and tumor cell type are all important prognostic factors that were not accounted for herein." (PMID 36398623, 2023). "Tumor DNA from a cohort of 100 UM patients from Moorfields Biobank (UK) that had undergone enucleation were sequenced for known UM driver genes (BAP1, SF3B1, EIF1AX, GNAQ, and GNA11)." (PMID 36077643, 2022). "Examining the 11 major oncogenes and tumor suppressors in UVM revealed that EIF1AX showed a significant sex difference in mRNA accumulation and copy number variation, with female tumors expressing higher levels of EIF1AX and exhibiting more variations in copy numbers." (PMID 34436011, 2021).
cancer (24 papers, 2011 to 2025). A tumor composed of atypical neoplastic, often pleomorphic cells that invade other tissues. "The EIF1AX gene encodes a vital eukaryotic translation initiation factor and EIF1AX mutations have been linked to several cancers." (PMID 39558949, 2024). "Despite its mutations in many cancers and its role in promoting mammary epithelial cell proliferation, the functions of EIF1AX in cancer, and the cellular mechanisms underlying these functions are poorly understood." (PMID 32926483, 2020). "Through exome and targeted sequencing we identified somatic EIF1AX mutations in 1.7% of SBTs and 15% of LGSCs, and one mixed grade carcinoma." (PMID 26506417, 2015). "EIF1AX is the only PIC subunit known to be recurrently mutated in cancer to date." (PMID 32926483, 2020). "Mann-Whitney U tests in TARGET and TCGA mRNA profiles showed a female bias in all tested cancer types for EIF1AX and 21 cancer types for EIF1AXP1 (p-value < 0.05)." (PMID 39975298, 2025). "Finding BRAF mutations or PPARG, NTRK1, NTRK3 and ALK fusions were strong predictors of a higher risk of cancer (approaching 100%) while other mutations like RAS, PTEN and EIF1AX or THADA fusions were associated with a significant but lower risk of cancer." (PMID 37510219, 2023). "Dysregulation of eukaryotic translation initiation factor 1A, X-linked (EIF1AX), has been implicated in the pathogenesis of some cancers." (PMID 36589683, 2022). "Frequently mutated in a number of cancer types including carcinomas and UVM, EIF1AX is considered a novel oncogenic driver." (PMID 34436011, 2021). "We found that EIF1AX mRNA was significantly upregulated in carcinoma tissues and the expression of EIF1AX was positively correlated with histological grades." (PMID 32926483, 2020). "Cancer prognosis can be determined based on the mutation status of additional genes like BRCA1-associated protein-1 (BAP1), Splicing Factor 3B Subunit 1 (SF3B1), and eukaryotic translation initiation factor 1A x-linked (EIF1AX)." (PMID 40283643, 2025). "RAS mutations are considered weak as they are common in benign thyroid neoplasms and other cancers, whereas RET, NTRK, and ALK rearrangements, along with mutations in BRAF, EIF1AX, and the TERT promoter, are termed strong and are often associated with malignant tumors." (PMID 39744583, 2025). "Strikingly, these included five cases (EIF1AX, HIST1H3B, MLH1, RPS15, SMARCB1) where not only the gene/protein, but also the region primarily mutated in human cancers were very ancient and could be traced back to unicellular organisms." (PMID 32731489, 2020). "The x-linked translation initiation factor, EIF1AX, is the most recently described significantly mutated gene in UM and has not been functionally characterized in cancer." (PMID 28594900, 2017). "Taken together, these data are consistent with EIF1AX being universally essential in eukaryotic cells, and suggest that cancer cells retain this dependency for pre-initiation complex assembly, growth, and survival, although further functional validation in each cancer type is necessary." (PMID 28594900, 2017). "Notably, when Bethesda IV nodules were malignant, they frequently harbored EIF1AX mutations, which did not typically result in aggressive cancer." (PMID 39766147, 2024). "On a pan-cancer scale, we replicated prior findings of sex-chromosome dosage-dependent gene essentiality in the DepMap CRISPR knockout screen in DDX3X, EIF1AX, ZFX and MAGEH117." (PMID 39975298, 2025).